SLC7A5 (solute carrier family 7 member 5)
Description:
The heterodimer with SLC3A2 functions as a sodium-independent, high-affinity transporter that mediates uptake of large neutral amino acids such as phenylalanine, tyrosine, leucine, histidine, methionine, tryptophan, valine, isoleucine and alanine. The heterodimer with SLC3A2 mediates the uptake of L-DOPA (By similarity). Functions as an amino acid exchanger. May play a role in the transport of L-DOPA across the blood-brain barrier (By similarity). May act as the major transporter of tyrosine in fibroblasts (Probable). May mediate blood-to-retina L-leucine transport across the inner blood-retinal barrier (By similarity). Can mediate the transport of thyroid hormones diiodothyronine (T2), triiodothyronine (T3) and thyroxine (T4) across the cell membrane. When associated with LAPTM4B, the heterodimer formed by SLC3A2 and SLC7A5 is recruited to lysosomes to promote leucine uptake into these organelles, and thereby mediates mTORC1 activation. Involved in the uptake of toxic methylmercury (MeHg) when administered as the L-cysteine or D,L-homocysteine complexes. Involved in the cellular activity of small molecular weight nitrosothiols, via the stereoselective transport of L-nitrosocysteine (L-CNSO) across the membrane. Mediates the uptake of 3-iodo-L-tyrosine (MIT). Mediates the uptake of 3,5-diiodo-L-tyrosine (DIT). (Microbial infection) In case of hepatitis C virus/HCV infection, the complex formed by SLC3A2 and SLC7A5/LAT1 plays a role in HCV propagation by facilitating viral entry into host cell and increasing L-leucine uptake-mediated mTORC1 signaling activation, thereby contributing to HCV-mediated pathogenesis.
Synonyms: 4F2LC; E16; LAT1; MPE16; D16S469E; CD98
Tractability: Small molecule: a structure with a bound ligand is known; a high-quality ligand is known. Antibody: UniProt places it where antibodies can reach, with high confidence; its Gene Ontology location is reachable by antibodies, with high confidence; UniProt predicts a signal peptide or a membrane-spanning region; the Human Protein Atlas places it where antibodies can reach. PROTAC: UniProt records ubiquitination sites on it; ubiquitination databases record sites on it; its protein half-life has been measured; a small molecule that binds it is known.
Target class: Transporter; SLC07 Cationic amino acid transporter/glycoprotein-associated family; Electrochemical transporter; SLC03 and SLC07 families of heteromeric amino acid transporters (HATs); SLC superfamily of solute carriers
Safety:
Unwanted effects reported when the protein is acted on. In parentheses: how it was acted on, where the effect was seen, and who reports it.
adverse events (source: ClinPGx)
gastrointestinal toxicity (source: ClinPGx)
Gene: Protein-coding gene on chromosome 16 (87,830,016 to 87,869,507, reverse strand). Ensembl gene ENSG00000103257.
Subcellular location: Apical cell membrane; Cell membrane; Lysosome membrane
Subcellular location (Human Protein Atlas): Cytosol; Plasma membrane; Vesicles
Pathways (Reactome):
Hemostasis: Basigin interactions
Metabolism: Tryptophan catabolism
Transport of small molecules: Amino acid transport across the plasma membrane
Gene Ontology:
Molecular function: amino acid transmembrane transporter activity; antiporter activity; aromatic amino acid transmembrane transporter activity; L-leucine transmembrane transporter activity; L-tryptophan transmembrane transporter activity; neutral L-amino acid transmembrane transporter activity; protein binding; thyroid hormone transmembrane transporter activity; L-amino acid transmembrane transporter activity; peptide antigen binding; transmembrane transporter activity
Biological process: alanine transport; amino acid import across plasma membrane; isoleucine transport; L-histidine transport; L-leucine import across plasma membrane; L-leucine transport; L-tryptophan transmembrane transport; methionine transport; negative regulation of gene expression; neutral amino acid transport; phenylalanine transport; positive regulation of interleukin-17 production; positive regulation of interleukin-4 production; positive regulation of type II interferon production; proline transport; thyroid hormone transport; tryptophan transport; tyrosine transport; valine transport; xenobiotic transport; amino acid transmembrane transport; positive regulation of cytokine production involved in immune response; transport across blood-brain barrier; amino acid transport; cellular response to amino acid stimulus; and 13 more
Cellular component: amino acid transport complex; apical plasma membrane; cytosol; extracellular exosome; lysosomal membrane; membrane; microvillus membrane; plasma membrane; transmembrane transporter complex; basal plasma membrane; basolateral plasma membrane; external side of apical plasma membrane
Genetic constraint (gnomAD): Loss-of-function variants: 18 observed, 43.86 expected, observed/expected ratio (o/e) 0.41, 90% interval 0.28 to 0.61. The upper end of that interval is the gene's LOEUF score, 0.61, which puts it in group 2 of 6, group 1 being the genes least tolerant of losing a copy. Missense variants: 556 observed, 661.74 expected, observed/expected ratio (o/e) 0.84, 90% interval 0.78 to 0.9. Synonymous variants: 383 observed, 328.23 expected, observed/expected ratio (o/e) 1.17, 90% interval 1.07 to 1.27.
Gene-disease validity (ClinGen):
ClinGen rates the evidence that SLC7A5 causes each of these diseases.
complex neurodevelopmental disorder (autosomal recessive): Moderate. A disorder that involves more than one phenotype associated with the central nervous system, including but not limited to intellectual disability, autism, and seizures (epilepsy).
Homologues: Orthologues: chimpanzee SLC7A5 (99% identical), macaque SLC7A5 (98% identical), dog SLC7A5 (94% identical), pig SLC7A5 (93% identical), rat Slc7a5 (92% identical), mouse Slc7a5 (92% identical), guinea pig SLC7A5 (83% identical), tropical clawed frog slc7a5 (81% identical), zebrafish slc7a5 (79% identical), Drosophila melanogaster CG1607 (46% identical), Drosophila melanogaster mnd (45% identical), Caenorhabditis elegans aat-1 (44% identical), and 8 more. Paralogues in human: SLC7A8 (52% identical), SLC7A7 (47% identical), SLC7A10 (46% identical), SLC7A6 (46% identical), SLC7A11 (44% identical), SLC7A9 (42% identical), SLC7A13 (26% identical), SLC7A4 (24% identical), SLC7A3 (23% identical), SLC7A2 (23% identical), SLC7A1 (22% identical), SLC7A14 (21% identical).
Diseases named in the same sentence as SLC7A5 in open-access papers:
SLC7A5 is named in the same sentence as 169 diseases in open-access papers, as found by Europe PMC text mining. Sharing a sentence is not in itself a finding about the gene and the disease. The quoted sentences say what the papers report.
breast cancer (67 papers, 2012 to 2026). A primary or metastatic malignant neoplasm involving the breast. "Regarding breast cancer, high expression of SLC7A5 mRNA and protein was associated with poor patient outcome and endocrine resistance in luminal-type breast cancer." (PMID 40611146, 2025). "Another source from the literature reported that SLC7A5 is associated with an aggressive luminal subtype of breast cancer characterized by high proliferative activity controlled by MYC activity." (PMID 39852119, 2024). "The increased expression of SLC7A5 is also associated with poor prognosis in patients with breast cancer." (PMID 39852119, 2024). "High SLC7A5 mRNA expression levels are associated with poor prognosis in several cancer types, including breast cancer." (PMID 37731509, 2023). "The upregulation of SLC7A5 appears to be predominantly linked to cell survival in estrogen receptor positive (ER+) breast cancer subtypes, supporting amino acid metabolism during nutritional stress." (PMID 38082346, 2023). "Previous studies have shown that SLC7A5 is highly expressed in breast cancer, and positively associated with histopathological grade and the expression of proliferation marker Ki-67 and HIF-1α." (PMID 35986300, 2022). "High expression levels of miR-126 or low expression levels of SLC7A5 were associated with better overall survival, validating their role as potential prognostic biomarkers in ER+ breast cancer." (PMID 35328298, 2022). "Then, we investigated the association of prognosis with the combination of LLGL2 and SLC7A5 mRNA expression in ERα-positive breast cancer patients receiving adjuvant tamoxifen therapy." (PMID 36192404, 2022). "We identified that low LLGL2/SLC7A5 mRNA co-expression (LLGL2low/SLC7A5low) was associated with disease-free survival (DFS) compared with other combination groups in all breast cancer patients." (PMID 36192404, 2022). "Next, we investigated the association between SLC7A5 mRNA expression and the prognosis of breast cancer patients." (PMID 36192404, 2022). "Altogether, these findings indicate that the SLC7A5/SLC3A2 complex implicated in the proliferation of ER+ breast cancer leads to tumorigenesis and the aggressiveness phenotype." (PMID 32093034, 2020). "Co-expression of SLC7A5/SLC3A2 mRNA within the METABRIC cohort was used to determine the prognostic value in ER+/HER2− breast cancer, whereby the SLC7A5+SLC3A2+ subgroup was associated with poor clinical outcome." (PMID 32093034, 2020). "Due to the significant association of the SLC7A5+SLC3A2+ subgroup of patients with a high rate of mitotic activity (p < 0.0001), we next investigated if SLC7A5/SLC3A2 co-expression is associated with proliferation of ER+ breast cancer." (PMID 32093034, 2020). "In this regard, we observed that the SLC7A5+SLC3A2+ subgroup is associated with high levels of mitotic activity in patients with ER+ breast cancer." (PMID 32093034, 2020). "In this study, we report that high SLC7A5/SLC3A2 co-expression is associated with poor clinical outcome in ER+ breast cancer patients, while those in the other combinatorial subgroups showed a better outcome." (PMID 32093034, 2020). "Altogether, these findings indicate that high SLC7A5/SLC3A2 co-expression associates with aggressive features in ER+/HER2− breast cancer, leading to cancer progression and short survival." (PMID 32093034, 2020). "In multivariate analysis, SLC7A5 protein was an independent risk factor for shorter breast-cancer-specific survival only in ER+ high-proliferation tumours (p = 0.02)." (PMID 29566741, 2018). "In addition, upregulation of SLC7A5 in breast cancer is associated with decreased overall survival and enhanced proliferation through targeting AKT/mTORC1 pathway." (PMID 38705513, 2024). "After showing that SLC7A5/SLC3A2 co-expression was associated with a worse outcome in patients with ER+ breast cancer, we next asked whether SLC7A5/SLC3A2 co-expression correlates with endocrine sensitivity." (PMID 32093034, 2020).
breast cancer (continued). "SLC7A5 expression is associated with increased tumor size, high nuclear grade, high Ki-67 labeling index, ER negativity, and progesterone receptor (PR) negativity in breast cancer." (PMID 29562706, 2018). "In addition, SLC7A5 is associated with endocrine resistance in luminal-type breast cancer cells." (PMID 37731509, 2023). "HSPB1 regulates estrogen receptor-positive (ER+) breast cancer cell proliferation in a SLC7A5-dependent manner." (PMID 42208896, 2026). "The high expression of SLC7A5 promotes the proliferation of ER+ breast cancer cells, leucine absorption, and the induction of tamoxifen resistance, making SLC7A5 a necessary and sufficient condition for developing resistance to tamoxifen therapy." (PMID 39973065, 2025). "High co-expression of SLC7A5 and SLC3A2 in breast cancer tissue was significantly associated with aggressive tumour phenotypes, such as increased proliferation, invasion, and metastasis." (PMID 41154605, 2025). "SLC7A5 exhibits notable subtype specificity in breast cancer, with high expression in HER2+, ER+, and TNBC, and is associated with poor patient prognosis." (PMID 39973065, 2025). "SLC7A5 promoted cell proliferation of MCF-7 breast cancer cells through activating AKT/mTORC1 signaling pathway." (PMID 40611146, 2025). "The LLGL2 protein in the scribble complex was demonstrated to interact with the leucine transporter Slc7a5 to enhance the leucine uptake by ER + breast cancer cells, which promote cell proliferation and confer cancer cell drug resistance." (PMID 41274508, 2025). "Collectively, these results indicate that IRF5 promotes tryptophan metabolism in breast cancer cells and facilitates metastasis by transcriptionally upregulating SLC7A5 and IDO1." (PMID 41179282, 2025). "The increased expression of SLC7A5 has been described in all molecular biological subtypes of breast cancer." (PMID 39852119, 2024). "Another study found that co-expressed SLC7A5/SLC3A2 knockdown inhibited breast cancer cell proliferation and increased sensitivity to the tamoxifen." (PMID 39834939, 2024). "High expression of Lgl2 and SLC7A5 correlates with poor survival in ER+ breast cancer patients treated with Tamoxifen, and depleting these proteins restored Tamoxifen sensitivity." (PMID 38091012, 2024). "Researchers found that knockdown of SLC7A5 inhibited the proliferation, migration, and invasion of breast cancer cells and enhanced anti-cancer immunity in combination with anti-PD-1 therapy." (PMID 39834939, 2024). "The expression of the transmembrane amino acid transporter SLC7A5 is active in all molecular biological subtypes of breast cancer." (PMID 39852119, 2024). "One study reported that SLC7A5 potentiated the proliferation of luminal breast cancer cells by activating AKT/mTORC1 through phosphorylation." (PMID 39852119, 2024). "It was also found that inhibition of SLC7A5 impaired the growth of endocrine-resistant breast cancer cells." (PMID 38705513, 2024). "According to previous studies, SLC7A5 interference can inhibit breast cancer growth and promote CD8+ T cells function in tumor microenvironment of colorectal cancer." (PMID 38402198, 2024). "In estrogen-receptor positive (ER+) breast cancer, Lgl2 recruits and stabilizes the amino acid transporter SLC7A5 at the plasma membrane." (PMID 38091012, 2024). "For this report, we aimed to evaluate cellular responses to hypoxia-mimetic by CoCl2 in ER+ breast cancer cell lines and the possible influence on SLC7A5 expression." (PMID 38082346, 2023). "Ultimately, we used a similar workflow to our prior published work to examine the impact of SLC7A5, a gene with a drastically different role in metabolism, in breast cancer." (PMID 37819900, 2023). "The outcomes of the analyses revealed that the expression of SLC7A5 was significantly increased in patients with breast cancer, and the higher the expression of SLC7A5 was, the more advanced the tumor progression and the less differentiated the tumor cells." (PMID 37731509, 2023).
breast cancer (continued). "In a previous study, we found that SLC7A5 is positively correlated to hypoxia inducible factor (HIF) 1 in clinical breast cancer samples." (PMID 38082346, 2023). "According to previous studies, SLC7A5 is expected to become an emerging therapeutic target for breast cancer." (PMID 37731509, 2023). "In conclusion our study confirms increased SLC7A5 levels in breast cancer cells under hypoxia-mimetic conditions induced by CoCl2, in line with existing research." (PMID 38082346, 2023). "To validate the role of SLC7A5 in breast cancer development, we analyzed the clinical relevance of SLC7A5 in multiple datasets." (PMID 37731509, 2023). "This study also helps to shed light on the prognostic role of miR-126 and its potential target SLC7A5 in ER+ breast cancer that will need further validation in cohorts with larger sample sizes." (PMID 35328298, 2022). "Second, we demonstrated that low LLGL2/SLC7A5 mRNA co-expression (LLGL2low/SLC7A5low) was also an independent favorable prognostic factor both in all breast cancer patients and in Erα-positive breast cancer patients." (PMID 36192404, 2022). "LLGL2 was also reported to function with SLC7A5 at cell junctions and membranes in ERα-positive breast cancer cells, and LLGL2 interacts with SLC7A5 to promote cell proliferation." (PMID 36192404, 2022). "First, we showed that low LLGL2 or low SLC7A5 mRNA expression was an independent favorable prognostic factor in Erα-positive breast cancer patients." (PMID 36192404, 2022). "To understand the relationship between SLC3A2 and SLC7A5 in their ability to regulate the proliferation of ER+ breast cancer cells, we analyzed changes in the protein levels of each other." (PMID 35501367, 2022). "Positive associations were identified between low SLC7A5 mRNA expression and longer DFS in ERα-positive breast cancer patients receiving adjuvant tamoxifen therapy (P = 0.014)." (PMID 36192404, 2022). "Targeting SLC7A5 amino acid transport activity using JPH203 significantly suppressed the proliferation of breast cancer." (PMID 35986300, 2022). "In this study, we evaluated the prognostic value of co-expression of LLGL2 and SLC7A5 in primary breast cancer patients with long-term follow-up." (PMID 36192404, 2022). "In this study, we assessed the effects of LLGL2/SLC7A5 co-expression in predicting prognosis and response to tamoxifen therapy in ERα-positive breast cancer patients with long-term follow up." (PMID 36192404, 2022). "Low SLC7A5 mRNA expression was positively associated with favorable prognosis in both DFS and OS in all breast cancer patients analyzed (P = 0.002 and P = 0.0005, respectively)." (PMID 36192404, 2022). "Previous studies have demonstrated that SLC7A5 regulates AKT/mTOR pathway expression in breast cancer." (PMID 35986300, 2022). "Unexpectedly, SLC3A2-KD decreased the total protein levels of SLC7A5 in ER+ breast cancer cells, and conversely, SLC7A5-KD reduced total protein levels of SLC3A2." (PMID 35501367, 2022). "LLGL2low/SLC7A5low showed longer survival compared with high LLGL2/SLC7A5 mRNA co-expression (LLGL2high/SLC7A5high) and a positive trend of longer survival compared with other combination groups in ERα-positive breast cancer patients." (PMID 36192404, 2022). "Given that intracellular leucine and SLC7A5 have been proven to be responsible for the growth of ER+ breast cancer cells, intracellular glutamine is aberrantly exported from the cell to support the leucine-dependent cell proliferation." (PMID 36077501, 2022). "Our study showed that co-expression of LLGL2 and SLC7A5 mRNA is a promising candidate biomarker in early breast cancer patients." (PMID 36192404, 2022). "High expression of SLC7A5 mRNA and LAT1 protein was associated with poor prognosis in the luminal B type of breast cancer." (PMID 34681614, 2021).